LIF (LIF interleukin 6 family cytokine)
Diseases named in the same sentence as LIF in open-access papers (continued):
Sharing a sentence is not in itself a finding about the gene and the disease.
tumor (continued). "As previously indicated, in addition to the production of proinflammatory cytokines and acute phase reactant proteins, tumor cells produce specific cytokines such as LIF and PIF, among others." (PMID 37960292, 2023). "We further validated the expression of LIF in tumor tissues, which demonstrated that the expression of LIF in tumor cells was higher in patients with advanced-stage CRC than in those with early-stage CRC." (PMID 37360193, 2023). "In mouse models, LIF blockade leads to reduced tumor progression and was able to synergize with immune checkpoint blockade to extend survival." (PMID 37134077, 2023). "TGF-β can induce CAF to produce LIF, leading to fibroblast activation and the promotion of tumor cell invasiveness." (PMID 35740622, 2022). "Using tumor tissues collected from high-BMI and low-BMI cases, we have demonstrated that tumors from high-BMI patients exhibit increased levels of LIF compared to low-BMI patients." (PMID 36358818, 2022). "LIF is ectopically overexpressed in multiple solid tumours, exerting promoting activity in tumour growth, metastasis formation, and chemotherapy resistance." (PMID 36359879, 2022). "iCAF, in turn, can release leukemia inhibitory factor (LIF), which is responsible for maintaining an inflammatory state and inducing the recruitment of tumor-associated macrophages (TAMs)." (PMID 35892828, 2022). "The increased expression of specific factors such as TGF-β/TGF-β2, CXCL12, bone morphogenic protein 7 (BMP7), leukemia inhibitory factor (LIF), and Wnt signaling can break dormancy and promote tumor cell proliferation." (PMID 35892884, 2022). "Our results suggest iCAFs as the main cell type expressing IL6, CXCL12, and LIF in the tumor milieu, wherein these ligands promote immunosuppressive changes, such as macrophage polarization, toward the M2 phenotype." (PMID 35196078, 2022). "LIF is involved in tumor spread and metastasis, treatment resistance, and cachexia, and has also cancer biomarker potential." (PMID 35626130, 2022). "Consistently, silencing or neutralizing LIF in circFRAP1-overexpressing CAFs reduced their effect to enhance the sphere formation and apoptosis resistance of tumor cells under GEM treatment." (PMID 35045883, 2022). "TNF and other inflammatory cytokines that are produced by macrophages in the tumor microenvironment stimulate tumor cells to produce IL-6 and LIF, contributing to tumor growth." (PMID 35740622, 2022). "Inhibition of LIF signaling by genetic LIFR deletion, LIF knockdown, or treatment with LIF neutralizing monoclonal antibodies leads to a reduction in tumor progression in mouse PDAC models and decreases tumor engraftment and growth in PDAC xenograft models." (PMID 35565185, 2022). "It indicates that the malignant potential of LIF in ccRCC is reflected in promoting tumor migration." (PMID 35992780, 2022). "Instead, the most significant difference among tumor foci from same patient was microenvironment-related genes (such as LIF and CCL2), emphasizing the critical involvement of these genes in various tumor evolution routes." (PMID 34987659, 2022). "Collectively, these data suggest that expression of IL6/LIF in the tumor microenvironment is negatively correlated with response to AET." (PMID 36230597, 2022). "In summary, LIF promotes tumor progression by being aberrantly expressed in the early stages of cancer and increases the degree of malignancy by affecting the tumor microenvironment." (PMID 35740622, 2022).
tumor (continued). "LIF blockade results in TAM phenotypic changes, in which C-X-C motif chemokine ligand 9 (CXCL9) expression is elevated, and CD8+ T cells are recruited to the tumor, suggesting that LIF is involved in resistance to immune checkpoint blockade." (PMID 35740622, 2022). "Intriguingly, the mesenchymal tumor foci in the three mGBM patients consistently highly expressed two cytokines, i.e., LIF and CCL2." (PMID 34987659, 2022). "LIF is aberrantly secreted by tumour cells and promotes tumour progression in pancreatic and other solid tumours through aberrant activation of the LIF receptor (LIFR) and downstream signalling that involves the JAK1/STAT3 pathway." (PMID 36359879, 2022). "Increased serum LIF concentrations can increase tumor cell radiation resistance, inhibit DNA repair, and promote tumor recurrence." (PMID 35740622, 2022). "Immunohistochemistry was performed to assess IL6 and LIF expression in both the tumor cells and surrounding stroma." (PMID 36230597, 2022). "For some of these features, a practical clinical application can be set up as, for example, in the case of LIF, a pleiotropic cytokine sensitizing tumor cells to immunotherapy." (PMID 36551658, 2022). "We previously demonstrated that tumor microenvironment interleukin-6/leukemia inhibitory factor (IL6/LIF) cytokines induce tumor cell JAK-STAT signaling to promote cancer growth." (PMID 36230597, 2022). "LIF also participates to cross-talk between tumor cells and matrix fibroblasts to mediate the pro-invasive activation of stromal fibroblasts and promotes drug resistance to HDAC inhibitors." (PMID 35847866, 2022). "In PDAC cells, the LIF/TGFβ pathway promotes the epithelial mesenchymal transition and tumour aggressiveness and is regarded as a promising therapeutic target." (PMID 36359879, 2022). "Considering that LIF functions in a highly cell- and tissue type-specific manner, future studies are needed to elucidate the impact of LIF overexpression upon different cell types in the tumor microenvironment." (PMID 35440095, 2022). "In PCa, lncAMPC/LIF/LIFR axis predicts a higher tumor metastasis rate and lower relapse-free survival (RFS) in patients." (PMID 36175921, 2022). "Vimentin plays an important role in tumor invasion and metastasis, and its counter-regulation is a further evidence of the role that LIF/LIFR signaling plays in the modulation of EMT process." (PMID 35847866, 2022). "The ERp57/PDIA3 silencing seems to activate GB cells to produce IL24 (a tumor-suppressing protein) and leukemia inhibitory factor (LIF), inhibiting cell differentiation." (PMID 35109791, 2022). "It is well known that most patients with advanced PDAC are in a cachectic state, perhaps because LIF is highly expressed in the tumor cells, macrophages, and mast cells in the tumor microenvironment of PDAC patients." (PMID 35740622, 2022). "Tumor-derived LIF is a vital initiation factor of cachexia, leading to the progression of cachexia and a poor prognosis for patients with late stages of cancer." (PMID 35740622, 2022). "In a PDAC mouse model, inhibition of LIF and genetic depletion of its receptor resulted in increased sensitivity to gemcitabine treatment and impaired tumor growth." (PMID 35712663, 2022). "Previous evidences have shown the upregulation of LIF in solid tumor, which mediates the proliferation, invasion and metastasis of tumor cells." (PMID 34729101, 2021). "Leukemia inhibitory factor (LIF), a cytokine secreted by stromal myofibroblasts and tumor cells, has recently been highlighted to promote tumor progression in pancreatic and other cancers through KRAS-driven cell signaling." (PMID 33846527, 2021). "Another study using a soluble version of the LIFR as a ligand trap demonstrated that blocking of LIF signaling slows tumor progression in a mouse model of pancreatic cancer." (PMID 34716410, 2021).
tumor (continued). "In PDAC cells, LIF is the major cytokine responsible for STAT3 activation in tumor cells, a critical factor in PDAC initiation, progression, and maintenance." (PMID 33846527, 2021). "A recent example of this strategy has shown that targeted pharmacological LIF blockade slows tumor progression in a mouse model." (PMID 34771503, 2021). "LIF has been shown to be produced at high levels in a variety of tumor types and promotes proliferation, invasiveness, stemness, neuronal remodeling, and the epithelial-to-mesenchymal transition." (PMID 33846527, 2021). "While some human PDAC cells secrete LIF in an autocrine loop, much of the LIF in the tumor microenvironment is derived from the surrounding activated stellate cells." (PMID 33846527, 2021). "Tumor cell-derived LIF stimulates macrophages’ M2-type polarization through activating the STAT3 signaling pathway." (PMID 34604066, 2021). "LIF signaling promotes crosstalk between tumor cells and fibroblasts, and mediate pro-invasive activation of stromal fibroblasts." (PMID 34400617, 2021). "Along with IL-6, CAF-derived LIF has also been identified as a major promoter of suppression in the tumor microenvironment." (PMID 34203869, 2021). "Many cytokines secreted by the PSCs or tumor cells contribute to the development of PDAC such as LIF." (PMID 33783993, 2021). "It was also recently reported that the leukemia inhibitory factor (LIF) secreted by the tumor induces changes in the expression of AT, as well as serum levels of IL-6 and leptin, acting in a JAK-dependent manner." (PMID 33557173, 2021). "Recent studies have identified LIF expression in the tumor microenvironment as a major driver of PDAC progression." (PMID 33846527, 2021). "In PC models, STAT3 activity in tumor-infiltrating MDSCs correlated to increased PD-L1 levels and elevated plasma levels of IL6-type cytokines, such as LIF, suggesting a potential cross-talk mechanism promoting tumor immune evasion." (PMID 34945784, 2021). "CAFs are activated and, in some instances, reported to be epigenetically driven/reprogrammed by the tumor cells via the pro-inflammatory cytokine, like leukemia inhibitory factor (LIF), into a pro-invasive phenotype." (PMID 34680395, 2021). "Based on our results and the work of others, it is likely that LIF reprises its stem-factor role in cancer, promoting the survival of cancer stem cells to increase sphere formation and tumor growth." (PMID 33846527, 2021). "LIF signaling promotes crosstalk between tumor cells and fibroblasts and mediates pro-invasive activation of stromal fibroblasts." (PMID 34400617, 2021). "Antibody-based anti-LIF therapy was also effective in slowing tumor growth in cell line and patient-derived xenograft models of human PDAC4." (PMID 33846527, 2021). "Of note, LIF targeted therapy resulted in a statistically significant decrease in tumor growth as compared to untreated controls." (PMID 33630157, 2021). "It has been also demonstrated that the block of LIF/JAK/STAT signaling with EC330 (LIF inhibitor) in a xenograft mouse model of PC significantly decreased the tumor volume and coupled with a reduction of PD-L1 expression in tumor tissue." (PMID 34830179, 2021). "As a whole, it appears that LIF activation of both the JAK/STAT and PI3K/AKT pathways are associated with the promotion of tumor growth and metastasis." (PMID 34395259, 2021). "We also examined LIF status in EC using publicly available TNMplot analysis platform that enable comparison of gene expression between tumor and normal tissues using validated database." (PMID 34400617, 2021). "For instance, tumor-derived Leukemia inhibitory factor (LIF) transcription is enhanced by HIF1α signaling activation following cisplatin treatment." (PMID 34604066, 2021). "By contrast, the receptor of leukemia inhibitory factor (LIFR), whose ligand LIF belongs to the IL-6 family of cytokines, shows an anti-tumor effect through induction of dormancy in the bone." (PMID 34745140, 2021).
tumor (continued). "As LIF induced tumor cell metastasis ability, we investigated the potential downstream effector(s) of LIF in OSCC progression; thus, a mRNA microarray was performed." (PMID 31973037, 2020). "In pancreatic cancer, a blockade of LIF:LIFR:STAT3 signaling resulted in a decrease in the expression of CSC-associated markers (CD133, CD24, and CD44), a reduction in tumor initiation and formation, and an overall less aggressive phenotype." (PMID 32023849, 2020). "The results of western blotting showed that the expression of LIF was remarkably increased or decreased in circSEPT9 overexpressing or silencing xenograft tumor tissues compared with control groups respectively." (PMID 32264877, 2020). "On the other hand, LIF also controls the immune tumor microenvironment by hindering CD8+ T cell tumor infiltration and promoting the presence of pro-tumoral macrophages." (PMID 33022971, 2020). "On the other hand, compared with NPC patients with complete tumor remission, LIF is higher in serum samples from NPC patients who developed local recurrence after treatment." (PMID 32368302, 2020). "In the murine C26 colon carcinoma model, LIF emerged as an important tumor-derived factor that induced atrophy in myotubules." (PMID 33291708, 2020). "Functional studies conducted by them revealed LIF’s physiological significance in driving both tumor progression and chemoresistance." (PMID 32245422, 2020). "We found an inverse relationship between the rate of tumor formation and the defense responses induced by the injection of LIF and LIFR." (PMID 32651426, 2020). "Specifically, sera from male tumour-bearing mice had higher levels of pro-inflammatory and chemotactic cytokines, including IL-6 (9.8-fold higher), LIF (3.5-fold higher), GCSF (2.7-fold), and MIP-1β (2.6-fold)." (PMID 32451467, 2020). "Overexpression of LIF increased migration and invasion rate of tumor cells in both in vitro and in vivo." (PMID 32651426, 2020). "LIF also enhances tumor progression by promoting cell cycle progression and invasive activity of tumor cells via STAT3 activation, as is the case of other IL-6 family of cytokines." (PMID 32023940, 2020). "LIFR injection, individually or in combination with LIF, strongly inhibited the tumor growth to only 25% of the mice." (PMID 32651426, 2020). "The grade of LIF expression in each specimen was further classified based on the percentage of tumor cells stained as follows: level 0 (0% or <5%), level 1 (5–25%), level 2 (26–50%), level 3 (51–75%), and level 4 (>75%)." (PMID 31973037, 2020). "Accordingly, we detected the production of IL24, which is a tumor-suppressing protein, and LIF, which inhibits cell differentiation." (PMID 33153019, 2020). "Conversely, LIF inhibition in tumor cell conditioned media (CM) prevented CM-induced myotube atrophy in vitro, while genetic inactivation of STAT3 in myofibers was sufficient to suppress atrophy in vivo." (PMID 33329046, 2020). "Cytoplasmic LIF staining was found in nearly all cancer cells of the tumor nests for positive LIF staining." (PMID 31973037, 2020). "A gene expression analysis revealed that KIT levels were significantly lower, while those of LIF were significantly higher (overexpressed), in tumor tissues, compared to those of normal tissues." (PMID 33092068, 2020). "In the absence of doxycycline, control cells and cells expressing inducible sh-LIF showed comparable tumor initiation and growth rates." (PMID 31296870, 2019). "The concentrations of five cytokines out of 32 compounds analyzed on the array—IL-7, G-CSF, CCL11, LIF and VEGF—were higher in the tumor-associated adipose tissue than in normal mouse adipose tissue." (PMID 31752313, 2019). "After introducing doxycycline to mice bearing established xenograft tumors, those expressing inducible shRNA against LIF showed significantly reduced tumor growth when compared with controls." (PMID 31296870, 2019).
tumor (continued). "The crosstalk between tumor cells and fibroblasts confers pro-invasive properties and LIF is shown to mediate the pro-invasive activation of fibroblasts." (PMID 30899415, 2019). "LIF is a pleiotropic member of the IL-6 family of cytokines secreted as a soluble factor in the tumor microenvironment (TME)." (PMID 30899415, 2019). "Expression of an inducible shRNA against LIF significantly blocked the sphere-forming ability of human PDAC cells in vitro as well as tumor initiation and growth in vivo in a doxycycline-dependent manner." (PMID 31296870, 2019). "To estimate the effect of inhibiting LIF in a model, which reflects tumor heterogeneity in patients, we next tested LIF-neutralizing antibody in patient-derived xenografts (PDXs), which expressed detectable LIF protein." (PMID 31296870, 2019). "In contrast, LIF-neutralizing antibody along with gemcitabine significantly repressed tumor growth and increased overall survival." (PMID 31296870, 2019). "After 4 weeks, we measured the plasma LIF concentration in rats with xenografts of both cell types and in the non-tumor bearing control group." (PMID 30410674, 2018). "In summary, these results elucidate that magnolin promotes autophagy and cell cycle arrest through LIF/Stat3/Mcl-1 pathway, which in turn prevents the tumor growth of CRC." (PMID 29899555, 2018). "Next, we conducted immunohistochemical analyses to investigate the distribution of LIF expression in the tumor microenvironment by using 112 human tongue OSCC samples." (PMID 29444110, 2018). "LIF-positive CAFs were correlated with older age (p < 0.0001), sex (female) (p = 0.0029), and tumor invasion depth (p = 0.0012)." (PMID 29444110, 2018). "In contrast, LIF+/− tumors showed a lower frequency of invasion into local tissues and formed smaller tumor buds." (PMID 30504771, 2018). "Our current findings showed the presence of LIF in nuclei of normal basal epithelia but predominant expression in the cytoplasm of tumor cells, implying diverse functional roles in normal epithelial and cancer cells." (PMID 30504771, 2018). "Previously we showed that elevated LIF in the tumor microenvironment enhances cancer radioresistance and is associated with poorer recurrence-free survival." (PMID 30504771, 2018). "In an in-depth study, use of conditioned medium made from the commonly used C26 mouse tumor cell line led to the identification of LIF as the secreted peptide required for myotube atrophy." (PMID 28993738, 2017). "In order to test myotube atrophy from a second mouse tumor that is known for making high levels of LIF, Ehrlich ascites carcinoma cells were used in the same two treatment designs as C26 to treat C2C12 myotubes." (PMID 28993738, 2017). "Expression of LIF and its receptor are higher in tumor cells, pointing to a function for this cytokine beyond its proposed function in TAM polarization." (PMID 27215396, 2016). "Knockdown of endogenous miR-21 clearly abolished the promoting effect of LIF on EMT as well as the migration ability of tumor cells." (PMID 26716902, 2016). "miR-21 has been reported to promote the proliferation and growth of tumor cells, a phenotype that is also observed in cells with LIF overexpression." (PMID 26716902, 2016). "Overexpression of LIF promotes tumor cells to acquire mesenchymal features, including morphological changes of cells from epithelial-like to mesenchymal-like, increased expression levels of mesenchymal markers and decreased expression of epithelial markers." (PMID 26716902, 2016). "IL10 and the gene encoding its receptor IL10R were expressed mainly by TAMs, LIF and LIFR by tumor cells, IL6 and the genes for IL6 receptor subunits IL6R and IL6ST by both cell types." (PMID 27215396, 2016). "Taken together, results from this study identified an important function and a novel underlying mechanism of LIF in EMT and tumor metastasis." (PMID 26716902, 2016).